APOL1 (apolipoprotein L1)
Diseases named in the same sentence as APOL1 in open-access papers (continued):
Sharing a sentence is not in itself a finding about the gene and the disease.
kidney disease (continued). "Furthermore, a second hit (or modifier) such as HIV or COVID infection or systemic lupus erythematosus often precedes the development of APOL1-mediated kidney disease (AMKD)." (PMID 41043427, 2025). "This failure to understand the more common, insidious presentation of APOL1 kidney disease has resulted in speculation on various potential mechanisms." (PMID 40940784, 2025). "The strategy in our department is to perform APOL1 genotyping in all patients referred for investigation of kidney disease, regardless of cause, symptomatology, or severity, as long as they are of African origin." (PMID 38899219, 2024). "Perspectives regarding the mechanism and treatment of APOL1-related kidney disease are discussed, as well as speculations on additional APOLs functions, such as APOL6 involvement in adipocyte membrane dynamics through interaction with myosin-10 (MYH10)." (PMID 38478101, 2024). "Podocyte injury (podocytopathy) is the central feature of APOL1-mediated kidney disease." (PMID 38227370, 2024). "Accurate diagnosis of APOL1-mediated kidney disease may help advance precision medicine in nephrology." (PMID 39271961, 2024). "However, recent early-stage clinical trials of APOL1 inhibitors have emerged as a promising treatment option for APOL1-mediated kidney disease." (PMID 39271961, 2024). "This highlights the fact that high-risk APOL1 mutations are not necessarily the cause of kidney disease." (PMID 38899219, 2024). "We also showed that in individuals with APOL1 HR, polygenic scores computed from summary statistics for eGFR in AAs outperformed the most recently developed PRS3 (R2, 0.5% versus 0.2%), suggesting the polygenicity of kidney disease among APOL1 HR is better captured by these summary statistics." (PMID 37962879, 2024). "However, the clinical relevance of our results is strongly supported by recent reports that naturally occurring genetic inhibition of APOL1 pore function prevents APOL1-mediated kidney disease in humans." (PMID 38227370, 2024). "In general, these models support the notion that the kidney disease is a function of the expression level of the APOL1 in podocytes, and describe different mechanisms through which the risk variants may induce CKD (recently reviewed in detail)." (PMID 37925499, 2023). "Despite significant risk, further research is needed to understand why not all APOL1 variant carriers contract kidney disease." (PMID 36951457, 2023). "The number of at-risk individuals for APOL1-associated FSGS and kidney disease is considerable." (PMID 38036523, 2023). "Not all individuals carrying two APOL1 high-risk variants develop kidney disease and “second-hits” are required for deterioration in kidney function." (PMID 38993907, 2023). "Whether the APOL1 risk variants G1 and G2 differ in their biologic behavior to trigger APOL1 kidney diseases remains unclear." (PMID 37969018, 2023). "Since no other viruses causing similar kidney disease in patients with APOL1 RRVs has been identified, further factors, highly related to HIV infection, should participate in APOL1 upregulation." (PMID 36835304, 2023). "While G0 heterozygotes demonstrate relative protection from developing kidney disease, most people with APOL1 RRV alleles do not develop kidney disease." (PMID 36835304, 2023). "The strong association with APOL1 HRG may provide an additional strategy in the evaluation and management of kidney disease risk among these patients." (PMID 36227935, 2022). "In the kidney, APOL1 is expressed in podocytes and vascular components of the glomerulus, suggesting that it might play a role in renal diseases that affect the structure and function of these cells." (PMID 35159001, 2022). "On the other hand, the kidney disease risk variants do not replace APOL1 G0 in this regard but rather demonstrate the well-known cellular toxicity that also prevents RCC cell growth and hence tumorigenic potential." (PMID 35159001, 2022).
kidney disease (continued). "The high CKD risk in this case is attributed to the high frequency of two APOL1 risk variants (RV) APOL1 G1 and APOL1 G2, which are associated with kidney disease, as opposed to the wild-type APOL1 G0 allele." (PMID 35159001, 2022). "Whether disclosing APOL1 genetic testing results to patients of African ancestry and their clinicians affects blood pressure, kidney disease screening, or patient behaviors is unknown." (PMID 35244702, 2022). "Common variants in the apolipoprotein L-1 gene (APOL1) only found predominantly in West Africans, make up the 2 risk haplotypes termed G1 and G2, which are potent risk factors for a spectrum of kidney diseases but very rare in European ancestry individuals." (PMID 36580463, 2022). "In addition, if plasma APOL1 plays a role in kidney disease, then it will be important to develop pharmaceuticals that prevent plasma and urine APOL1 multimerization." (PMID 36279295, 2022). "Our current findings in human plasma and human urine, which are correlative and hypothesis-generating, as well as our data from APOL1 transgenic mice support a possible role for recipient APOL1 protein in the kidney disease process." (PMID 36279295, 2022). "Together, these data support a hypothesis in which circulating APOL1 enters the urine similar to albumin and may play a role in the development and progression of kidney disease." (PMID 36279295, 2022). "Although studies have determined that interferon upregulates APOL1 gene expression through binding of interferon-responsive elements, it remains unclear how this increased expression drives the development of kidney disease." (PMID 34350953, 2021). "Since most carriers of two risk alleles do not develop kidney disease spontaneously and the APOL1 variant expression itself was not sufficient to induce podocyte dysfunction, a second hit is postulated essential for the development of kidney disease." (PMID 35095882, 2021). "Some researches indicated APOL1 is related to cardiovascular disease and renal disease." (PMID 34315402, 2021). "Currently, two APOL1 inhibitors, i.e., VX-147 and the antisense oligonucleotide AZD2373 are being tested in Phase 2 (NCT04340362) and Phase 1 (NCT04269031) clinical trials, respectively, for the treatment of patients with APOL1-associated kidney disease." (PMID 34442464, 2021). "Collapsing glomerulopathy is a typical form of kidney disease in the APOL1 spectrum." (PMID 32892322, 2020). "It has not been fully clarified which APOL1 splice variants are expressed in the kidney and which of those contribute to kidney disease." (PMID 32854642, 2020). "Many individuals with a high risk genotype of two APOL1 variants, however, do not develop kidney disease." (PMID 31661509, 2019). "Hypertensive AAs without overt kidney disease who carry 1 or more APOL1 risk variants have a greater BP and albuminuria reduction in response to candesartan therapy." (PMID 31532792, 2019). "Given its importance, clinical testing for APOL1 variants is under discussion but unexplained variance remains, and evidence of kidney disease is not observed among all carriers of two high-risk variants." (PMID 31390993, 2019). "Risk variants in APOL1 are reported to be associated with increased cardiovascular disease, even without kidney disease." (PMID 31532792, 2019). "It has been suggested in multiple studies where participants had predominantly normal kidney function that APOL1 is a kidney disease gene and has not been significantly associated with eGFR55–57." (PMID 31451708, 2019). "HIVAN is therefore an important model disease, the study of which may hold important insights mechanisms by which APOL1 promotes kidney disease." (PMID 29930940, 2018). "Merely carrying high-risk APOL1 variants is not sufficient to cause kidney disease, and significant attention is currently being directed toward identifying second hits in the form of environmental and infectious triggers that promote disease development." (PMID 29713631, 2018).
kidney disease (continued). "Two apolipoprotein L1 (APOL1) susceptibility gene variants (G1 and G2) have been identified, with 88% higher risk of CKD progression in African Americans, and have also been suggested for the higher predilection of kidney disease in African blacks." (PMID 29903699, 2018). "Little is still known about the roles of APOL1 in kidney disease." (PMID 29903699, 2018). "In the absence of kidney disease, there does not appear to an obvious renal phenotype associated with the APOL1 risk variant." (PMID 27004159, 2016). "The mechanism behind APOL1-associated renal disease has not been elucidated, although the relation between APOL1 risk variants and podocyte injury is being investigated." (PMID 27004159, 2016). "To identify whether APOL1 protein expression is affected in human kidney disease, we stained human kidney sections against APOL1 and the specific podocyte marker nephrin." (PMID 27138898, 2016). "Since the current model predicts an increased risk for kidney disease with G1 and G2 in the absence of G0, a haplotype carrying two copies of APOL1 would reduce the chances of G0 being completely absent in a G1 or G2 positive individual." (PMID 25933006, 2015). "The associations of APOL1 with markers of early kidney disease did not vary by income category, or vice versa." (PMID 25884165, 2015). "In one branch of a large African American pedigree that we had ascertained previously because of the high rate of kidney disease in the family, we identified members of a nuclear family (woman, her brother, and her son) all with three copies of APOL1 by PCR assay." (PMID 25933006, 2015). "Despite evidence of an association between variants at the apolipoprotein L1 gene (APOL1) locus and a spectrum of related kidney diseases, underlying biological mechanisms remain unknown." (PMID 26025194, 2015). "APOL1 variants are in strong linkage disequilibrium with MYH9 variants, and it remains controversial whether MYH9 variants play a direct role in kidney disease risk." (PMID 22956460, 2013). "The two identified APOL1 risk alleles were noted to be in strong linkage disequilibrium with the MYH9 risk haplotype, and association between APOL1 and kidney disease remained significant after further adjustment for this and other combinations of the MYH9 alleles." (PMID 23782479, 2013). "Similar efforts undertaken more recently to control for APOL1 and look for second sites of significant association with kidney disease also have not been fruitful." (PMID 23300552, 2012). "Thus, the APOL1 pore function inhibitor can potentially complement the effects of these drugs in the treatment of kidney disease patients, especially among Africans with a high burden of kidney disease and where the frequency of APOL1 high-risk alleles is high." (PMID 40027896, 2025). "If low nephron endowment is a contributor to some presentations of insidious APOL1 kidney disease, the current anti-APOL1 drugs in clinical testing may be ineffective in these cases since ongoing APOL1 expression is not driving podocyte loss and the ensuing proteinuria and eGFR decline." (PMID 40940784, 2025). "To highlight the value of UM30-OSN in modeling APOL1-mediated kidney disease with an APOL1 (G1/G0) genotype, we examined how Interferon-γ (IFN-γ) affects UM30-OSN–derived podocytes and assessed whether the JAK1/JAK2 inhibitor Baricitinib can counteract IFN-γ–induced cellular responses." (PMID 41225540, 2025). "Not all people with high-risk APOL1 variants develop kidney disease." (PMID 40027896, 2025). "In this study, we present a comprehensive analysis of APOL1 plasma pQTLs in individuals of African descent, comparing data from the UK Biobank, generated with Olink’s technology, and the African American Study of Kidney Disease and Hypertension (AASK), generated with SomaLogic’s technology." (PMID 39975113, 2025).
kidney disease (continued). "If the mechanism of low nephron endowment underlies insidious APOL1 kidney disease, clinical trials testing anti-APOL1 drugs may not be efficacious in these cases since ongoing APOL1 expression in the kidney would not be driving podocyte injury and loss." (PMID 40940784, 2025). "This association was consolidated by two independent follow-up studies that showed significant association between a lack of functional APOL3 and increased risk for kidney disease, with only one of these having the power to also demonstrate an APOL1 interaction effect." (PMID 40643530, 2025). "In conclusion, CRISPR-based genotyping may help making accurate diagnosis of APOL1-mediated kidney disease widely accessible due to its increased speed and cost-effectiveness as compared to Sanger sequencing, thereby enabling early preventative measures and monitoring of disease." (PMID 39271961, 2024). "However, many patients with two APOL1 risk variants never develop renal disease, leading researchers to propose a two-hit model in which genetic susceptibility combined with an inflammatory trigger leads to disease." (PMID 37882666, 2023). "Thus, the risk of kidney disease mediated by genetic variants in APOL1 follows an autosomal recessive inheritance, unlike more common complex variants that follow an additive or multiplicative pattern." (PMID 36588788, 2022). "Presented APOL1 risk alleles confer susceptibility, but most subjects with two risk alleles may not develop kidney diseases." (PMID 35408886, 2022). "It should also be noted that although the presence of the high-risk genetic variants increases the susceptibility to several kidney diseases, most individuals with APOL1 high-risk variants will not develop kidney disease, harming the ability to predict the patient’s lifetime risk." (PMID 36588788, 2022). "Therefore, the upstream activator of APOL1-mediated kidney disease may be increased dimerization and channel formation by G1 and G2 owing to decreased hairpin stability of the monomer." (PMID 34331942, 2021). "However, individuals with the high-risk genotype of APOL1 do not universally suffer from kidney disease." (PMID 35145920, 2021). "Therefore, transgenic expression of human APOL1 in mice does not seem to cause any apparent kidney disease, irrespective of APOL1 genotype." (PMID 34350953, 2021). "Furthermore, the dependency of channel activity on oligomer formation may also have implications for APOL1-mediated kidney disease." (PMID 34331942, 2021). "However, not all individuals with two risk alleles develop diagnosed kidney disease, and less is known about the natural history of those with a single APOL1 risk allele." (PMID 31532792, 2019). "However, not all individuals with 2 APOL1 risk alleles will develop kidney disease, and we have relatively little knowledge of the natural history of APOL1 risk carriers." (PMID 31532792, 2019). "These clinical trials with well phenotyped and genotyped essential hypertensive subjects present an opportunity to gain insights and an understanding of the natural history of APOL1 risk allele carriers in AA hypertensives without evidence of overt kidney disease." (PMID 31532792, 2019). "The absence of the APOL1 gene in most primates except humans, gorillas, and baboons has been a major obstacle for testing causality between risk alleles G1 or G2 and development of kidney disease." (PMID 29880816, 2018). "Transgenic mice expressing the G0 or G2 alleles of APOL1 in podocytes under control of the nephrin promoter do not develop kidney disease but mice expressing the G2 but not the G0 allele in podocytes under control of the podocin promoter developed FSGS lesions." (PMID 29930940, 2018). "Plasma APOL1 levels do not correlate with risk of kidney disease." (PMID 29930940, 2018).
kidney disease (continued). "It suggested that there was a significant difference in the variation of APOL1 among different races, and there might be other variations in the APOL1 gene, rather than G1 or G2, associated with the kidney diseases in Caucasian or Asian population." (PMID 28800731, 2017). "Therefore, the finding of diminished levels of APOL1 protein expression and mRNA stability for APOL1 G1 and G2 compared with G0 is not a plausible explanation for the pathogens of cell injury or for kidney disease risk." (PMID 28385815, 2017). "The data presented here is consistent with that hypothesis, but no support was found for the role of the G2 allele of APOL1 (rs71785313) in HAT although it is implicated in kidney disease." (PMID 29059176, 2017). "Interestingly, some individuals carrying APOL1 risk alleles do not develop kidney disease highlighting the role of additional genetic or environmental interactions." (PMID 27148508, 2016). "It is not known how the APOL1 G1 and G2 variants lead to kidney disease." (PMID 27054572, 2016). "The varied presentations of APOL1 kidney disease may in part result from placental APOL1 expression and its effect on nephron endowment, since the insidious presentation of APOL1 kidney disease has many similarities to kidney disease attributed to prematurity and low birth weight." (PMID 40940784, 2025). "In conclusion, the authors propose that hyperactive αvβ3 integrin due to APOL1 RRV led to proteinuria and kidney disease in mice." (PMID 40643483, 2025). "Nonetheless, transgenic (Tg) rodent models have been used to characterize the molecular mechanism through which the APOL1-RA and HIV-1 genes induce renal diseases." (PMID 40747773, 2025). "If low nephron endowment is a causal mechanism behind some forms of APOL1 kidney disease, this may have an impact on clinical trials evaluating drugs directly inhibiting APOL1, since in these instances, ongoing APOL1 expression may not be driving podocyte loss and progressive kidney dysfunction." (PMID 40940784, 2025). "Beyond APOL1 induction, the effects of IFN-γ are complex and present a confounding variable in studying kidney disease." (PMID 38838223, 2024). "Thus, kidney disease induced by APOL1 risk variants may result not from intrinsic APOL1 toxicity, but rather from improper cell function and consecutive inflammatory reaction." (PMID 38478101, 2024). "Dpep1 and Chmp1a levels also strongly and negatively correlated in mouse models of kidney disease induced by UUO, FA, APOL1, and PGC1a." (PMID 34426578, 2021). "Similarly, most individuals with two APOL1 risk alleles do not develop kidney disease." (PMID 30417125, 2018). "Although possession of the APOL1 risk variants in an autosomal recessive manner increases susceptibility to nondiabetic kidney disease, not all people who possess these variants develop kidney disease, which indicates that another factor may initiate progression of kidney disease." (PMID 29903699, 2018). "The reversal from clearance to enhanced boarding of HIV-1 as a function of the non-risk WT versus risk G1 or G2 alleles state of APOL1, may explain why, of all podocytopathic kidney diseases, HIVAN shows the most striking odds ratio, reading >89 in one recent study." (PMID 27599995, 2016). "Thus, despite the highly significant association between high-risk APOL1 and kidney disease among African Americans in multiple recent studies, it may not be the only contributor to early kidney disease in this population." (PMID 25884165, 2015). "Here, we used zebrafish as an in vivo model to study the consequences of gene perturbation and potential synergistic effects of APOL1 and MYH9 in kidney disease." (PMID 26147622, 2015). "In the APOL1-HR group (1413 participants), M1 was significantly inversely associated with FSGS or SRNS cases compared with controls without kidney disease (OR, 0.20; 95% CI, 0.04-0.63; P = 3.69 × 10-3)." (PMID 41811315, 2026).